CUL4B (cullin 4B)
Diseases named in the same sentence as CUL4B in open-access papers (continued):
Sharing a sentence is not in itself a finding about the gene and the disease.
tumor (continued). "In the TCGA-UCEC dataset, APOBEC3G, CUL4B, SCML2, TSPYL5, and ZBTB16 were significantly downregulated in tumor samples, whereas FOXP3, HJURP, HMGB3, and RAC3 were significantly upregulated in tumor samples, which was generally consistent with the result observed in GSE17025." (PMID 36936912, 2023). "CUL4B catalyzes histone ubiquitination (H2AK119) and facilitates the recruitment of polycomb repressive complex 2 (PRC2) to repress the expression of various tumor-suppressor genes, most importantly PTEN and p16." (PMID 37686215, 2023). "In our previous work, we showed that CUL4B was significantly upregulated in PM tumor tissues compared to non-cancerous inflammatory pleural tissues." (PMID 37686215, 2023). "Altogether, gene expression data from the publicly available databases support our hypothesis regarding the role of CUL4B in the regulation of TGF-β signaling, as well as the tumor microenvironment in PM tumors." (PMID 37686215, 2023). "SIRT1 and CUL4B were found to be significantly upregulated in tumors, with their level of expression positively correlated with tumor histological grades, while FOXO3 expression was negatively correlated with tumor histological grades." (PMID 34163012, 2021). "Our data suggested that CUL4B might serve as a treatment target for MPM and revealed novel mechanism of pevonedistat in the MPM tumor microenvironment." (PMID 33233664, 2020). "In contrast, a hypoxia-induced decrease in cullin 4B (CUL4B) was observed in both cell types, which has been reported to restrict myeloid-derived suppressor cells (MDSC) accumulation prohibiting the establishment of a tumor-permissive microenvironment." (PMID 31959767, 2020). "CUL4 paralogs (CUL4A and CUL4B) were upregulated in MPM tumor specimens compared to nonmalignant pleural tissues." (PMID 33233664, 2020). "In TCGA cohort, CUL4B expression was correlated with Tumor, Lymph node and Metastasis (TNM) stage (none of the stage 4 patients received neoadjuvant treatment), and Gleason score." (PMID 30872583, 2019). "Compared to a negative control (ShSCR), shRNA-mediated knockdown of CUL4B (shCULB) significantly inhibited the growth of VCaP tumor xenografts." (PMID 30872583, 2019). "Here, we show that CUL4B is upregulated in non‐small‐cell lung carcinoma (NSCLC) tissues and is critically required for cell proliferation and migration in vitro and for xenograft tumor formation in vivo." (PMID 28164432, 2017). "We next investigated whether CUL4B and MLN4924 affect the tumor metabolism in ccRCC." (PMID 40419474, 2025). "In addition, we demonstrated that CUL4B regulates TGF-β1 signaling in PM cells and this may affect the tumor microenvironment in part by signaling macrophage recruitment." (PMID 37686215, 2023). "We first examined the expression of Cul4B in 4 tumor tissue and paired non-tumor tissues." (PMID 32622365, 2020). "Furthermore, we constructed human and murine CUL4B (SYBC1)/Cul4b (MB49)-KO cell lines and found that tumor cells lacking CUL4B showed enhanced STING stability and IFN-β production under treatment of cisplatin, RT, or cGAMP." (PMID 37670034, 2023).
infection (3 papers, 2023 to 2024). The state of being infected such as from the introduction of a foreign agent such as serum, vaccine, antigenic substance or organism. "Moreover, the CUL4B activator etoposide alleviates disease development in a mouse infection model, suggesting that this agent or its derivatives may be used to treat infections caused by SARS-CoV-2." (PMID 38265236, 2024). "Early in infection, an ASFV ubiquitin-conjugating enzyme (I215L) binds to eIF4E, inducing its overexpression, and to cullin 4B (CUL4B), which regulates mTOR activity." (PMID 37631977, 2023). "These defects in T cell responses resulted in a severe defect in viral control as mice lacking Cul4b in T cells continued to show high titers of virus at a time point when most control mice had cleared infection." (PMID 37925424, 2023).
neurodevelopmental disorder (2 papers, 2019 to 2020). A behavioral and cognitive disorder with onset during the developmental period that involves impaired or aberrant development of intellectual, motor, or social functions. "Four of the identified genes (CUL4B, HDAC8, MED12, and USP9X) have been previously reported to harbor de novo PTVs and Dmis variants in male cases with neurodevelopmental disorders, providing more genetic evidence of their pathogenicity." (PMID 33023636, 2020). "However, how loss of function of Cul4B causes these neurodevelopmental disorders is not well established." (PMID 31170139, 2019).
adenocarcinoma (1 paper, 2017). A common cancer characterized by the presence of malignant glandular cells. "We further examined CUL4B expression in normal lung, primary adenocarcinomas, nearby lymph nodes with or without metastasis, and distant metastatic lesions." (PMID 28164432, 2017).
brain diseases (1 paper, 2020). "Cul4B has been recently identified to play an important role in regulating TSC2 and mTOR signaling in some brain diseases, and it is also able to degrade 4E-BP2 eukaryotic translation initiation factor." (PMID 33384682, 2020).
kidney diseases (1 paper, 2024). "Yet, the role of CUL4B in kidney diseases is poorly investigated." (PMID 39695153, 2024).
metabolic disease (1 paper, 2025). A congenital disorder (due to inherited enzyme abnormality) or acquired (due to failure of a metabolically important organ) disorder resulting from an abnormal metabolic process. "CUL4B plays a significant role in metabolic diseases, particularly in the regulation of adipose tissue and insulin sensitivity." (PMID 40230836, 2025). "In metabolic diseases, CUL4B regulates adipose tissue and insulin sensitivity, with its depletion improving metabolic phenotypes." (PMID 40230836, 2025).
neurological disorders (1 paper, 2024). "Our work provides mechanistic insights into the pathogenesis of the neurological disorders in XLID patients with CUL4B mutations." (PMID 38331954, 2024).
CUL4B also shares sentences with these, for which no sentence is quoted: central obesity (4 papers); cognitive deficits (2); genetic disorder (2); multiple myeloma (2); Angelman syndrome (1); Breast Tumor (1); cerebrooculofacioskeletal syndrome 1 (1); Cockayne syndrome B (1); colitis (1); epilepsy (1); female infertility (1); gastrointestinal tumor (1); Hypergonadotropic hypogonadism (1); hypogonadism (1); immune dysfunction (1); intellectual disability syndromes (1); leukodystrophy (1); lymphoid neoplasm (1); ovarian tumor (1); pancreatic adenocarcinoma (1); pancreatic ductal adenocarcinoma (1); Pes cavus (1); Primary amenorrhea (1); primary immunodeficiency (1); psychiatric diseases (1); Seizure (1); small cell lung carcinoma (1); Spinocerebellar ataxia type 3 (1); T-cell lymphoma (1); thymoma (1).
A further 5 diseases each share a sentence with CUL4B in 1 paper.